TNF (tumor necrosis factor)
Diseases named in the same sentence as TNF in open-access papers (continued):
Sharing a sentence is not in itself a finding about the gene and the disease.
tuberculosis (continued). "Tumor-necrosis-factor-α inhibitors (anti-TNF-α) are associated with an increased risk of tuberculosis (TB) disease, primarily due to reactivation of latent TB infection (LTBI)." (PMID 36335186, 2023). "Populations receiving immunosuppressive therapy, such as tumor necrosis factor-alpha (TNF) antagonists, systemic corticosteroids, or immunosuppressive drug therapy following organ transplantation, are at the greatest risk for active tuberculosis." (PMID 37298620, 2023). "The use of immunosuppressants such as TNF inhibitors, corticosteroids and other immunosuppressants in patients infected with latent M. tuberculosis increases the risk of progression to active tuberculosis." (PMID 37764964, 2023). "TNF inhibitors have been declared as the target specific treatment for RA, by blocking TNF and decreasing the inflammatory response, but they also have an increased risk of tuberculosis." (PMID 37763713, 2023). "Long-term use of anti-TNFα agents has been associated with the risk of serious infections, malignancies, skin and soft tissue infections, and tuberculosis." (PMID 37554981, 2023). "As reported in the literature, anti-TNF therapies significantly increase the risk of infectious AEs, mainly the risk of severe infections and tuberculosis." (PMID 37111283, 2023). "As anti-TNF-α agents have the potential to increase the risk of serious infections such as bacteremia, pneumonia, tuberculosis." (PMID 37248486, 2023). "The use of tumor necrosis factor inhibitors, for example, is associated with an increased risk of tuberculosis and of infection caused by NTM." (PMID 35198325, 2022). "A meta-analysis including 78 studies with 24 996 patients highlighted that anti-TNF drug use is associated with an increase in the occurrence of infections (+20%), serious infections (+40%), and tuberculosis (+250%)." (PMID 36296168, 2022). "Ustekinumab has been shown to exhibit a 14-fold lower risk of developing tuberculosis compared to anti-TNF-α therapy." (PMID 36362709, 2022). "Lastly, we confirmed the validity of this study by showing the increased risk of tuberculosis in the matched TNF inhibitor cohort." (PMID 35945635, 2022). "TNF-α is similar to above three biomarkers and can diagnose tuberculosis, showing a high diagnostic efficacy." (PMID 35345666, 2022). "The risk of tuberculosis development was confirmed to be higher in TNF inhibitor users in the matched (adjusted HR: 2.816; 95% CI, 1.243–6.383), but not the unmatched cohort (adjusted HR, 0.886; 95% CI, 0.612–1.283)." (PMID 35945635, 2022). "Possible associations with the risk of serious infections, opportunistic infections, tuberculosis (TB), demyelinating disorders, and lymphoma have been reported for other TNF inhibitors (TNFi)." (PMID 35313978, 2022). "The risk of tuberculosis was significantly increased by TNF inhibitors (incidence rate ratio = 3.61 with a 95% CI 1.38–8.07 for patients with RA and incidence rate ratio = 4.87 with a 95% CI 1.50–15.39 for patients with AS)." (PMID 36430392, 2022). "Three widely used anti-TNF-α drugs with long-term safety profiles-infliximab and adalimumab-have been indicated to increase the risk of developing tuberculosis, which is similar to our finding." (PMID 34776944, 2021). "As such, treatment with tumor necrosis factor alpha (TNF‐α) blocking agents increases the risk of tuberculosis, Pneumocystis jirovecii infection and aspergillosis, and meta-analyses have reported increased risk for serious infectious complications." (PMID 33530653, 2021). "Tuberculosis (TB) is more specifically associated with the use of tumor necrosis factor alpha antagonists." (PMID 33593700, 2021). "Three studies involving 3,092 patients with RA, PsA, or AS evaluated anti-TNFα drugs and reported an insignificant difference in the risk of tuberculosis following treatment with anti-TNFα agents." (PMID 34790122, 2021).
tuberculosis (continued). "Infections associated with anti-tumor necrosis factor antibody therapy include tuberculosis, viral, fungal, and bacterial infections." (PMID 32150046, 2020). "In humans, anti-TNF-α drugs lead to increased risk of contracting infectious diseases, such as tuberculosis." (PMID 32116590, 2020). "Summary of case reports of anti-tumor necrosis factor α-induced tuberculosis associated-immune reconstitution inflammatory syndrome." (PMID 33120729, 2020). "Among TNF inhibitors, etanercept is associated with the lowest incidence of tuberculosis and a longer duration of lag time for reactivation of tuberculosis." (PMID 32987907, 2020). "At the same time, the risk of tuberculosis is increased in patients treated with immunosuppressive drugs, especially TNF-α antagonists." (PMID 33233818, 2020). "The study also demonstrated that phloretin exhibited safe and effective properties for reducing tuberculosis and associated lung inflammation by decreasing the effects of tumor necrosis factor-α (TNF-α) and interleukin-β." (PMID 32630150, 2020). "The use of anti-TNF (infliximab and adalimumab) agents also significantly increases the risk of tuberculosis (TB) infection and malignancies." (PMID 32731605, 2020). "Pre-clinical and clinical evidence indicate that anti-TNF-α therapy (infliximab, adalimumab, golimumab, certolizumab pegol, and etanercept) is associated with a 2- to 4-fold increase in the risk of active tuberculosis and other granulomatous conditions." (PMID 31134083, 2019). "RA and its medication, especially TNF-α inhibitors, increase the risk of clinical tuberculosis (TB) infection." (PMID 31528842, 2019). "RA and its medication, especially TNF-α inhibitors (TNFi), increase the risk of active tuberculosis (TB) infection." (PMID 31528842, 2019). "Especially, the main concern regarding anti-TNF therapy, as well as other biological agents, is the greater susceptibility to infections such as interstitial lung disease, pneumonia, sepsis, and tuberculosis (TB)." (PMID 31608149, 2019). "Both studies evaluated whole blood samples from HIV-associated tuberculosis participants, which were stimulated with bacterial antigens and heat-killed M. tuberculosis, and observed lower TNF-α production upon stimulation in participants with a poor outcome." (PMID 31276515, 2019). "On the other hand, the use of monoclonal antibodies targeting cytokines, such as tumor necrosis factor alpha has revealed new risk groups for infections, such as tuberculosis." (PMID 31134083, 2019). "Anti-TNF therapy is associated with higher rate of tuberculosis, especially with the monoclonal antibodies; adalimumab and infliximab." (PMID 31057626, 2019). "Currently, there were some researches on the relationship between TNF-α gene polymorphism and tuberculosis, but the results were contrary." (PMID 31072917, 2019). "Another constraint is the high risk of reactivation of tuberculosis in countries with high burden, especially with the use of tumor necrosis factor blocking agents." (PMID 31057626, 2019). "Opportunistic infection such as tuberculosis is another major concern associated with TNF-α blockers due to their potential pro-infective action." (PMID 30412634, 2018). "In humans, therapeutic blockade of TNF-α leads to an increased risk of reactivation of some diseases, especially tuberculosis." (PMID 29543912, 2018). "For instance, anti-TNF inhibitors cause serious side effects, including cancer, tuberculosis, or pneumonia." (PMID 30079020, 2018). "We have demonstrated that the TNF-α–only TEFF cellular immune signature associates closely with the single strongest risk factor for progression of LTBI to tuberculosis in immunocompetent adults: time since infection." (PMID 28329119, 2017). "In animal studies, similar cytokine profile was observed as in CNS-TB patients, and the genetic deficiencies of immune effectors such as TNF and iNOS have confirmed its importance as critical for immune protection against tuberculosis in the CNS." (PMID 28280495, 2017).
tuberculosis (continued). "Side effects, such as an increased risk of fungal infections and of tuberculosis for the patients with latent Mycobacterium tuberculosis infections, are escalated after anti-TNF-α therapy, or some patients poorly respond to this therapy." (PMID 29463951, 2017). "TNF inhibitors, in particular, have been associated with an increased risk of serious infections, including reactivation tuberculosis, bacterial sepsis, invasive fungal infections (such as histoplasmosis), and infections due to opportunistic pathogens." (PMID 29273067, 2017). "The role of TNF in immune protection against tuberculosis was primarily derived from observations in TNFR deficient mice, which do not assemble well-formed granuloma." (PMID 28824652, 2017). "Etanercept is considered the safest anti-TNF inhibitor in terms of the possible risk of serious infection (notably tuberculosis reactivation)." (PMID 29184553, 2017). "First, recent strategies to treat LTBI decrease tuberculosis reactivation associated with TNF inhibitor by 80%, while long term use of TNF inhibitors drive recipients susceptible to new tuberculosis infection in the intermediate tuberculosis burden area." (PMID 27101309, 2016). "Recently, individualized introduction of TNF inhibitors or DMARDs according to AS disease activity and risk of tuberculosis activation has been proposed in an expert opinion." (PMID 27101309, 2016). "In a 3-year French study of 69 newly diagnosed tuberculosis patients undergoing anti-TNF therapy, it was concluded that anti-TNF antibodies (infliximab and adalimumab) have a high risk for tuberculosis." (PMID 28083070, 2016). "Risk factors for tuberculosis in autoimmune disease include use of anti-TNF monoclonal antibody, old age, rheumatic disease itself, concomitant disease-modifying antirheumatic drugs (DMARDs), glucocorticosteroids and previous tuberculosis infection history." (PMID 27101309, 2016). "Non-TNF biologics such as ustekinumab and secukinumab can be alternatives to AS patients who experienced TNF inhibitor-associated tuberculosis, are currently being introduced as new biologics for AS." (PMID 27101309, 2016). "It has long been known that these agents, particularly the tumor necrosis factor-alpha (TNFα) inhibitors such as Infliximab, put patients at increased risk for opportunistic infections and reactivation of latent infections such as tuberculosis." (PMID 27818806, 2016). "In our registry, the most frequently resumed TNF inhibitor was etanercept, a recombinant protein of soluble TNF receptor, which has been considered having lesser risk of tuberculosis compared to monoclonal antibodies." (PMID 27101309, 2016). "Adult patients receiving anti-TNFα drugs are at increased risk of tuberculosis (TB), but studies in pediatric populations are limited, and the best strategy for latent tuberculosis infection (LTBI) screening in this population remains controversial." (PMID 26635208, 2015). "Principal component 2 (PC2) reflected pro-inflammatory and Th1-polarized cytokine responses due to its positive loading with IFN-γ, IL-17 and TNF, responses more commonly associated with acute schistosome infection or bacterial infections such as tuberculosis." (PMID 26291831, 2015). "The present study was aimed to evaluate the levels of TNF-α, IL-10 & IL-6 cytokines and their correlation with genotype variants amongst tuberculosis patients and their household contacts." (PMID 26359865, 2015). "The crucial role of TNF in controlling mycobacterial infection is exemplified by the increased risk of tuberculosis in patients with chronic inflammatory disorders treated with TNF antagonists." (PMID 24973749, 2014). "Studies reveal that tuberculosis risk varies with the use of different anti-TNF-α agents (etanercept, 35 cases per 100,000 patients; infliximab, 144 per 100,000 patients; and adalimumab, 240 per 100,000 patients)." (PMID 24884602, 2014).
tuberculosis (continued). "Anti-TNF-α immunotherapy has been associated with increased risk of tuberculosis reactivation due in part to a decrease in antimicrobial activity and CD8+ effector memory T cell activation." (PMID 24402617, 2014). "Here, we report a disseminated non-tuberculosis case caused by TNF-α inhibitor therapy and a probable paradoxical response to antimycobacterial therapy." (PMID 24576098, 2014). "The tuberculosis risk ratio for adalimumab, which is a humanized antibody against TNF-α, was reported to be even higher at 19.9 (95% CI, 16.2-24.8) fold according to the data for a Spanish population." (PMID 25317081, 2014). "The anti-TNF drugs are associated with unusual and atypical viral and fungal infections, tuberculosis, and bacterial infections." (PMID 26425605, 2014). "Larger studies should be performed to evaluate the absolute risk of severe infection, including tuberculosis, and compare with other strategies of TNF blockade." (PMID 25517733, 2014). "Among 16 risk factors immunosuppressive therapy, HIV-infection and treatment with TNF-antagonist were thought to be the most important risk factors for the development of tuberculosis in Germany." (PMID 25393241, 2014). "For example, an increased risk of serious tuberculosis and other opportunistic infections has been reported with TNF-blocking agents across various studies, and that effect is likely directly related to the target molecule." (PMID 24620738, 2014). "The macrophage-activating cytokine IFN-γ on the other hand together with TNF-α is a well known pivotal cytokine in the control of mycobacterial infections, as illustrated by the increased susceptibility to tuberculosis in IFN-γ gene disrupted mice." (PMID 24392169, 2014). "On the contrary, the carriers of genotypes associated with low TNF production show a higher frequency of tuberculosis and virus hepatitis infection." (PMID 23343370, 2013). "Chronic infections like tuberculosis are usually accompanied by anemia because of lowered Epo production caused by cytokines such as tumor necrosis factor." (PMID 23601138, 2013). "In agreement with experimental studies, we suggest that in tuberculosis LT-α only acts as an auxiliary to TNF-α in granuloma maintenance, and deficiency of the latter cytokine has a greater impact on disease reactivation." (PMID 23824716, 2013). "The risk of tuberculosis reactivation and opportunistic bacterial infection is a pitfall of treatment with anti-TNF and other biologic agents." (PMID 23505550, 2013). "Formation of granuloma occurs in response to a persistent stimulus and has also been linked with TNF and induction of host matrix metalloproteinase (MMPs) production in tuberculosis." (PMID 24192007, 2013). "The association between the use of tumor necrosis factor-α inhibitors and the increased risk of granulomatous infections, especially tuberculosis, has been well documented." (PMID 23304607, 2012). "Both, loss and overproduction of TNF-α have fatal effects on the outcome of tuberculosis, be it due to a loss of granuloma structure and excessive pathology or due to impaired macrophage activation." (PMID 23110184, 2012). "A fixed effect model was takentook to estimate pooled OR with 95% confidence interval (CI) for the association between the TNF -238G/A polymorphism and tuberculosis susceptibility." (PMID 23192010, 2012). "Blockade of TNF, however, has been associated with the reactivation of tuberculosis and the possible development of other opportunistic infections such as histoplasmosis, listeriosis and pneumocystis." (PMID 23285227, 2012). "The introduction of biologic therapy has increased the incidence of tuberculosis (TB) infections, all tumor necrosis factor (TNF) antagonists being associated with activation of latent tuberculosis infection." (PMID 27536430, 2012). "The relationship between the TNF -238G/A polymorphism and tuberculosis susceptibility remains inconclusive." (PMID 23192010, 2012).
tuberculosis (continued). "One concern with anti-TNF-α Ab therapy, however, is that TNF-α is essential for protection against Mycobacterium tuberculosis (TB), and it has, in fact, been reported that anti-TNF-α Ab therapy is associated with reactivation of tuberculosis." (PMID 21603208, 2011). "Macrophages play a central role in host defense against mycobacterial infection and anti- TNF therapy is associated with granuloma disorganization and reactivation of tuberculosis in humans." (PMID 22114556, 2011). "The screening strategies employed in Europe and North America have reduced the occurrence of TNF-α inhibitor-associated tuberculosis." (PMID 20606887, 2010). "While it is tempting to suggest multiple administrations, this would risk the possibility of compromising immunity towards pathogenic agents, as seen with the TNF-inhibitors causing reappearance of infectious diseases such as tuberculosis." (PMID 20102615, 2010). "The increased risk of tuberculosis and other opportunistic infections in patients receiving TNFα blockers is now well known." (PMID 20637100, 2010). "There was, however, a SNP in TNF-α that was associated with tuberculosis among all study participants." (PMID 20196868, 2010). "Neutralization of TNF-α for treating rheumatic diseases increases the risk of reactivation and outbreak of tuberculosis and other opportunistic infections." (PMID 20633267, 2010). "The combination of two SNPs in TLR4 (C→T) (rs1399431) and TNF-α (C→T) (rs7791836) predicted tuberculosis risk with 71% accuracy in blacks (P = 0.02)." (PMID 20196868, 2010). "Systemically reduced TNF levels, e.g. in the presence of TNF targeted biologicals have been shown to significantly enhance the risk of reactivation of tuberculosis in latently infected individuals." (PMID 20652022, 2010). "Patients receiving anti–tumor necrosis factor-α (anti–TNF-α) therapy are at increased risk for tuberculosis and other granulomatous diseases, but little is known about illness caused by nontuberculous mycobacteria (NTM) in this setting." (PMID 19861045, 2009). "The increasing use of anti-TNFα biological agents in RA is a major step forward, but its use is restricted by an associated risk of infection, including tuberculosis." (PMID 18593464, 2008). "The use of the TNF alpha antagonist Infliximab® is associated with reactivation of latent tuberculosis and requires concomitant use of anti-tuberculosis prophylaxis." (PMID 18596984, 2008). "Treatment with anti-TNF alpha monoclonal antibodies and corticosteroids increase the risk of opportunistic infections including tuberculosis." (PMID 19077197, 2008). "Small-molecule inhibitors (tofacitinib) and biologic therapies such as anti-TNF, anti-integrin, and anti-IL-12/23 can increase susceptibility to infections (e.g., tuberculosis, opportunistic fungal infections) and, in rare cases, lead to the development of lymphomas or demyelinating disorders." (PMID 40283915, 2025). "This suggests that tuberculosis-associated systemic inflammation may exacerbate organ dysfunction through a TNF-α/IL-1β positive feedback loop, providing new insights for precise interventions in comorbid populations." (PMID 40831574, 2025). "The use of TNF-α inhibitors enhances tuberculosis susceptibility and incidence by 1.6–25.1 times." (PMID 40371340, 2025). "Furthermore, TNF-α inhibitors reduce the apoptosis of macrophages infected with tuberculosis and hinder immune cell migration, reducing tuberculosis clearance and raising risk." (PMID 40371340, 2025). "TNF-α inhibitors disrupt granuloma formation by reducing pro-inflammatory signals, leading to the apoptosis of immune cells that maintain the granulomas, which allows trapped Mycobacterium tuberculosis to escape and cause active tuberculosis." (PMID 40763141, 2025). "Furthermore, the pathogenic effect of TNF-α has been well documented since overexpression can cause damage to multiple organs, causing lung dysfunction during tuberculosis." (PMID 38672491, 2024).